VANGL2 (VANGL planar cell polarity protein 2)
Diseases named in the same sentence as VANGL2 in open-access papers (continued):
Sharing a sentence is not in itself a finding about the gene and the disease.
tumor (15 papers, 2014 to 2025). "In basal breast cancer, the archetypal Wnt/PCP protein VANGL PCP protein 2 (VANGL2) is upregulated and is associated with poor prognosis and tumour growth through the VANGL2‐p62/SQSTM1‐JNK pathway." (PMID 32391621, 2020). "Based on merge data from TCGA and GTEx, we evaluated the expression status of VANGL2 in tumor and normal tissues." (PMID 39871948, 2024). "We assessed the functional importance of Vangl2 to mammary tumorigenesis and tumor cell metastatic dissemination by specifically ablating Vangl2 in the mammary epithelium of MMTV-NDL mice." (PMID 37147680, 2023). "Vangl2 also mediates Wnt-dependent signaling through RhoA and JNK by interacting with Mutated in Colorectal Cancer (Mcc), a presumed tumor suppressor, through its C-terminus, to regulate CE in zebrafish." (PMID 35646914, 2022). "The positive association between the expression of DDR1 with genes SOX9, CTNNB1, or VANGL2 emphasizes its role in stemness and tumor aggressivity." (PMID 35664781, 2022). "Our results on the inhibitory effect of VANG-1/Vangl on canonical Wnt signaling provide a mechanistic explanation for the role of Vangl2 as a tumor suppressor gene." (PMID 30532125, 2018). "In conclusion, circIGF1R acts a tumor suppressor in NSCLC by inhibiting the Wnt pathway through the VANGL2/miR-1270 axis, RBFOX3 promotes circIGF1R biogenesis by binding to IGF1R pre-mRNA, and is induced by paclitaxel to inhibit the migration and invasion of NSCLC cells." (PMID 38191906, 2024). "A total of 625 tumours (23%) showed VANGL2 mRNA upregulation compared with normal breast (NB)." (PMID 26754771, 2016). "The reduced tumour growth of VANGL2-depleted cells was confirmed by in vitro assays." (PMID 26754771, 2016). "We demonstrate the involvement of VANGL2 in tumour growth in cell culture and mice." (PMID 26754771, 2016). "We next addressed whether the VANGL2–p62/SQSTM1 complex and its associated JNK signalling pathway have a significance in tumour progression." (PMID 26754771, 2016). "Despite similar kinetics of primary tumor initiation and growth in Vangl2+/+/NDL and Vangl2fl/fl/NDL mice, Vangl2-depleted tumors are significantly less metastatic than Vangl2-intact tumors." (PMID 37147680, 2023). "The tumor cells adapting to brain tissue do provide several pro-angiogenic functions temporarily, e.g. in BN25 15, Plxnd1, Vangl2, Fzd2, Fzd5, and Vegfa promote patterning of blood vessels and vascular development." (PMID 25004123, 2014). "VANGL2-depleted SUM149 and HCC1806 cells xenografted into NOD/SCID/γc null female mice (NSG) showed reduced in vivo tumour growth compared with cells transfected with shLuc." (PMID 26754771, 2016). "Taken together, these findings may suggest that the reduced incidence of metastasis observed upon Vangl2 ablation is the result of reduced dissemination from the primary tumor rather than suppressed outgrowth of colonies in the lungs." (PMID 37147680, 2023). "Mammary gland-specific knockout of Vangl2 results in a striking decrease in lung metastases in MMTV-NDL mice, but does not impact primary tumor growth characteristics." (PMID 37147680, 2023).
infection (4 papers, 2014 to 2024). The state of being infected such as from the introduction of a foreign agent such as serum, vaccine, antigenic substance or organism. "Compared with the control group, infection of BMDMs from Vangl2-CKO mice resulted in 2224 differentially expressed genes (1001 up-regulated and 1223 down-regulated)." (PMID 37352355, 2023). "Here, our discovery of Vangl2–PDLIM2–NDP52 complex in the regulation of p65-mediated NF-κB signaling could be a therapeutic target for the development of immunotherapy against infection and inflammation." (PMID 39269442, 2024). "Third, consistent with the research about TRAF3IP3, we constructed the in vivo infection model using mice specifically lack VANGL2 in myeloid cells to verify the harmful role of VANGL2 in vivo, especially in macrophages, which differs from the study about USP38 that used USP38-KO mice." (PMID 37352355, 2023). "To test whether PCP pathway components are involved in A–P guidance of corticospinal axons, we designed and packaged short hairpin RNA (shRNA)-expressing lentivirus targeting Ryk, Vangl2, Fzd3 or Dvl1 for in vitro infection studies." (PMID 28660073, 2017).
genetic diseases (1 paper, 2024). "Along the same line, mutations in the human VANGL1 and VANGL2 genes have been linked to genetic diseases characterized by neural tube closure defects." (PMID 38403249, 2024).
metabolic disorder (1 paper, 2021). "Collectively, our results indicate that Vangl2 silencing protects chondrocyte from IL-1β-induced metabolic disorder in vitro." (PMID 33588909, 2021).
renal disorders (1 paper, 2024). "Our findings hold significance as they reveal variations in the immunoexpression of ITGA8 and VANGL2 throughout typical human kidney development and in renal disorders." (PMID 39064873, 2024).
VANGL2 also shares sentences with these, for which no sentence is quoted: autosomal dominant polycystic kidney disease (1 paper); brain cancer (1); cholangiocarcinoma (1); cognitive defects (1); coronavirus disease 2019 (1); Cyclopia (1); diffuse large B-cell lymphoma (1); fibrosarcoma (1); glomerulosclerosis (1); inflammatory bowel disease (1); injury (1); intellectual disabilities (1); Kidney Cyst (1); kidney damage (1); kidney malformations (1); lipoma (1); low grade glioma (1); lung squamous cell carcinoma (1); lymphedema (1); lymphoid neoplasm (1); Meningomyelocele (1); metastatic disease (1); microencephaly (1); muscular dystrophy (1); neural tube defect (1); ovarian carcinoma (1); paraganglioma (1); pheochromocytoma (1); Renal cyst (1); renal fibrosis (1).
A further 8 diseases each share a sentence with VANGL2 in 1 paper.